CENPX (centromere protein X)
Description:
DNA-binding component of the Fanconi anemia (FA) core complex. Required for the normal activation of the FA pathway, leading to monoubiquitination of the FANCI-FANCD2 complex in response to DNA damage, cellular resistance to DNA cross-linking drugs, and prevention of chromosomal breakage. In complex with CENPS (MHF heterodimer), crucial cofactor for FANCM in both binding and ATP-dependent remodeling of DNA. Stabilizes FANCM. In complex with CENPS and FANCM (but not other FANC proteins), rapidly recruited to blocked forks and promotes gene conversion at blocked replication forks. In complex with CENPS, CENPT and CENPW (CENP-T-W-S-X heterotetramer), involved in the formation of a functional kinetochore outer plate, which is essential for kinetochore-microtubule attachment and faithful mitotic progression. As a component of MHF and CENP-T-W-S-X complexes, binds DNA and bends it to form a nucleosome-like structure. DNA-binding function is fulfilled in the presence of CENPS, with the following preference for DNA substates: Holliday junction > double-stranded > splay arm > single-stranded. Does not bind DNA on its own.
Synonyms: CENP-X; FAAP10; MHF2; STRA13; MGC14480; D9
Tractability: PROTAC: ubiquitination databases record sites on it.
Gene: Protein-coding gene on chromosome 17 (82,018,590 to 82,024,107, reverse strand). Ensembl gene ENSG00000169689.
Subcellular location: Nucleus; Chromosome, centromere; Chromosome, centromere, kinetochore
Pathways (Reactome):
Cell Cycle: Deposition of new CENPA-containing nucleosomes at the centromere
DNA Repair: Fanconi Anemia Pathway
Immune System: PKR-mediated signaling
Gene Ontology:
Molecular function: DNA binding; double-stranded DNA binding; protein binding
Biological process: interstrand cross-link repair; replication fork processing; resolution of meiotic recombination intermediates; chromosome segregation; positive regulation of protein ubiquitination; DNA repair; kinetochore assembly
Cellular component: chromatin; FANCM-MHF complex; Fanconi anaemia nuclear complex; inner kinetochore; nucleus; cytosol; nucleoplasm; chromosome, centromeric region
Genetic constraint (gnomAD): Loss-of-function variants: 13 observed, 12.21 expected, observed/expected ratio (o/e) 1.06, 90% interval 0.69 to 1.66. The synonymous counts are far from expectation, so gnomAD's model fits this gene poorly and the ratio says little. Missense variants: 138 observed, 96.17 expected, observed/expected ratio (o/e) 1.43, 90% interval 1.25 to 1.65. Synonymous variants: 66 observed, 42.45 expected, observed/expected ratio (o/e) 1.55, 90% interval 1.27 to 1.87.
Homologues: Orthologues: guinea pig CENPX (81% identical), rat Cenpx (78% identical), dog CENPX (77% identical), rabbit CENPX (74% identical), macaque CENPX (73% identical), tropical clawed frog CENPX (58% identical), zebrafish cenpx (52% identical), Caenorhabditis elegans F35H10.5 (22% identical).
Diseases named in the same sentence as CENPX in open-access papers:
CENPX is named in the same sentence as 11 diseases in open-access papers, as found by Europe PMC text mining. Sharing a sentence is not in itself a finding about the gene and the disease. The quoted sentences say what the papers report.
breast carcinoma (1 paper, 2021). "The FA genes we identified as DEGs; CENPX, FAAP24, FANCD2, FANCI, UBE2T and FANCA are all overexpressed in breast cancer." (PMID 33662042, 2021).
diabetes (1 paper, 2019). "Our findings highlight CENPX inhibition as a potential therapeutic strategy for diabetes control." (PMID 31417608, 2019). "We next performed knockout and knockdown studies in zebrafish and mouse models of T2DM and elucidated that centromeric protein X (CENPX) may be a potential therapeutic target in diabetes." (PMID 31417608, 2019).
Hyperglycemia (1 paper, 2019). An increased concentration of glucose in the blood. "Inhibition of CENPX expression in zebrafish and mouse diabetic models led to the amelioration of hyperglycemia through the induction of insulin secretion." (PMID 31417608, 2019).
tumor (4 papers, 2015 to 2022). "With regard to associations between gene expression and tumor diameter, we noticed an association between low expression of WDR48 and XPC and a large LBD (p = 0.01 and p = 0.004, respectively), while a high expression of CENPX correlated with a large LBD (p = 0.02)." (PMID 31382494, 2019). "Conversely, some well-known factors related to tumor growth promotion, such as HMGA1, GTF3A, PHF19, CENPX, and MBD2, were upregulated." (PMID 35935940, 2022).
CENPX also shares sentences with these, for which no sentence is quoted: Fanconi anemia (6 papers); infection (2); cancer (1); leukemia (1); liver cancer (1); Obesity (1); type 2 diabetes mellitus (1).